FOXM1 (forkhead box M1)
Diseases named in the same sentence as FOXM1 in open-access papers (continued):
Sharing a sentence is not in itself a finding about the gene and the disease.
lung adenocarcinoma (continued). "By integrating the ChIP-seq data with RNA-seq data generated upon the knockdown of MYBL2 and FOXM1, we revealed that MYBL2 and FOXM1 act as transcriptional activators in lung adenocarcinoma." (PMID 36291764, 2022). "We discovered that MYBL2 regulates cell cycle genes by binding to the promoters of highly expressed genes in lung adenocarcinoma cells working with FOXM1." (PMID 36291764, 2022). "In this study, we performed MYBL2 and FOXM1 ChIP-seq, identifying global binding sites of MYBL2 and FOXM1 in lung adenocarcinoma cells for the first time." (PMID 36291764, 2022). "A549 lung adenocarcinoma cells treated with FDI-6 show significant reductions in FOXM1 protein accumulation in nuclei." (PMID 36291764, 2022). "To explore the clinical relevance of FOXM1 and PD‐L1 in patients with adenocarcinoma, we analyzed the survival curves of lung adenocarcinoma (LUAD) in The Cancer Genome Atlas (TCGA) dataset on cBioPortal." (PMID 35975458, 2022). "To target the oncogenic activities of MYBL2 and FOXM1 in lung adenocarcinoma, we have explored ways to suppress them using an inhibitor." (PMID 36291764, 2022). "We also found that cyclin B1 (CCNB1) is regulated by MYBL2 and FOXM1, and overexpression of CCNB1 is associated with poor survival of lung adenocarcinoma patients." (PMID 36291764, 2022). "We demonstrated that FDI-6 decreases the proliferation of lung adenocarcinoma cells and inhibits the activities of FOXM1 as well as MYBL2." (PMID 36291764, 2022). "Our results demonstrated that MYBL2 and FOXM1 cooperatively regulate the G2/M phase transition cell-cycle genes in lung adenocarcinoma cells." (PMID 36291764, 2022). "Here, a pan-cancer analysis of FOXM1 was conducted by the TCGA database and FOXM1 expression was verified in lung adenocarcinoma (LUAD)." (PMID 36435510, 2022). "This is the first study on the mechanism of berberine in the treatment of lung adenocarcinoma by regulating FOXM1 and POLE2 mediated by FOXM1." (PMID 35173608, 2021). "In our study, the expression of FoxM1 was down regulated in lung adenocarcinoma cells after berberine treatment, most significantly in H1975 cells." (PMID 35173608, 2021). "In order to evaluate the role of FOXM1 in DNA replication of lung adenocarcinoma cells, we further analyzed the transcriptional regulation of related differential genes in DNA replication pathway." (PMID 35173608, 2021). "In vivo, we also found that berberine inhibited the survival of lung adenocarcinoma xenografts and significantly down regulated the expression of FOXM1." (PMID 35173608, 2021). "In conclusion, berberine intervened the survival of lung adenocarcinoma cells by inhibiting the expression of POLE2 mediated by FOXM1." (PMID 35173608, 2021). "In agreement, FOXM1 was recently identified as a key transcriptional regulator of cancer-specific enhancers in lung adenocarcinoma." (PMID 34205406, 2021). "FoxM1 had recently been identified as a key transcriptional regulator of related oncogenes in lung adenocarcinoma." (PMID 35173608, 2021). "HGF/cMET signaling stimulates the expression and transcriptional activity of FOXM1 via its downstream pathways in pancreatic ductal adenocarcinoma and lung adenocarcinoma cells." (PMID 33806615, 2021). "Berberine inhibited the proliferation of lung adenocarcinoma cells by interfering with the expression of POLE2 involved in DNA replication mediated by transcription factor FOXM1." (PMID 35173608, 2021). "Subsequent survival analyses confirmed that overexpression of MYBL2 outperformed both E2F1 and FOXM1 transcription factors in identifying lung adenocarcinoma patients with poor outcomes." (PMID 33489883, 2020). "We identified individual lung adenocarcinoma enhancers linked to CENPA, FOXM1, or MYBL2 that were associated with poor patient survival." (PMID 32925947, 2020).
lung adenocarcinoma (continued). "ALKBH5 was found to influence the proliferation and invasion of lung adenocarcinoma cells under intermittent hypoxia (IH) conditions by reducing m6A modification of FOXM1 mRNA and promoting FOXM1 expression." (PMID 32398132, 2020). "High expression of CENPA, FOXM1, and MYBL2 is particularly observed in a subgroup of lung adenocarcinomas and is associated with poor patient survival." (PMID 32925947, 2020). "Intermittent hypoxia‐induced ALKBH5 amplification in lung adenocarcinoma promotes cell proliferation and invasion by decreasing the m6A level of FOXM1 mRNA and increasing the translation of FOXM1 mRNA." (PMID 33029866, 2020). "FOXM1 (forkhead box transcription M1) is a nuclear co-activator participating in lung adenocarcinoma (LUAD)." (PMID 32513952, 2020). "FOXM1 cDNA expression is increased > 2-fold in squamous cell carcinoma and adenocarcinoma of the lung." (PMID 30992007, 2019). "Silencing of FOXM1 expression by siRNA in A549 lung adenocarcinoma cells resulted in significant reduction in cell cycle-promoting cyclin A2 and cyclin B1 genes, as well as DNA replication and mitosis." (PMID 31681566, 2019). "In the present study, we found that FOXM1 is necessary and sufficient to induce mucinous characteristics in lung adenocarcinomas induced by either urethane or KrasG12D." (PMID 29267283, 2017). "We have developed a mouse model of mucinous, metastatic lung adenocarcinomas and demonstrated that FOXM1 is necessary and sufficient to induce mucinous phenotype in lung tumor cells." (PMID 29267283, 2017). "Taken together, these results strongly suggested that FOXM1 was involved in mediating the response to gefitinib in lung adenocarcinoma cell lines." (PMID 27494877, 2016). "To test the significance of FOXM1 interference in lung adenocarcinoma cells, we transfected pcDNA3.1-FOXM1 plasmid into PC9 and HCC827 cells, and transfected FOXM1 shRNA into PC9/GR and HCC827/GR cells." (PMID 27494877, 2016). "First, we found that FOXM1 was involved in mediating the response to gefitinib, and attenuated cell apoptosis and G1 arrest effects of gefitinib in lung adenocarcinoma cells." (PMID 27494877, 2016). "Inhibition of pAKT by LY294002 or inhibition of pMET by PHA-665752 significantly inhibited the expression of FOXM1 in lung adenocarcinoma cells." (PMID 27494877, 2016). "Collectively, these results indicate that FOXM1 activates the AKT pathway through MET in lung adenocarcinoma cells." (PMID 27494877, 2016). "In the present study, two gefitinib-sensitive lung adenocarcinoma cell lines and their sub-lines with enhanced gefitinib resistance were studied to systemically address the role of FOXM1 in gefitinib resistance of lung adenocarcinoma cells." (PMID 27494877, 2016). "To better understand the molecular mechanism by which FOXM1 contributes to gefitinib resistance in lung adenocarcinoma cells, we searched for the potential targets of FOXM1." (PMID 27494877, 2016). "We examined the expression levels of FOXM1 and related molecules in lung adenocarcinoma cells by western blot and quantitative real-time PCR." (PMID 27494877, 2016). "Our study demonstrated that FOXM1 activated the MET/AKT signaling pathway by stimulating the transcription of MET in lung adenocarcinoma cells, and this effect was partially inhibited by PHA-665752." (PMID 27494877, 2016). "In this study, we characterized the critical role of transcription factor Forkhead box protein M1 (FOXM1) in gefitinib resistance of lung adenocarcinoma cells." (PMID 27494877, 2016). "Depletion of Foxm1 mRNA in cultured lung adenocarcinoma cells significantly decreased TOPO-2α mRNA and protein levels." (PMID 19672312, 2009). "Depletion of Foxm1 mRNA in cultured lung adenocarcinoma cells significantly decreased TOPO-2α mRNA and protein." (PMID 19672312, 2009). "Foxm1 induced TOPO-2α expression in A549 lung adenocarcinoma cells and directly bound to the TOPO-2α promoter region." (PMID 19672312, 2009).
lung adenocarcinoma (continued). "Other bimodally expressed genes identified in our analyses, such as FOXM1, MELK, RGS20, and OIP5, have been previously reported to associate with clinical outcomes and play functionally significant roles in lung adenocarcinoma." (PMID 40427178, 2025). "Moreover, our findings are consistent the operation of a positive feedback loop between the expression of KPNA2 and FOXM1, which contributes to enhancing the proliferation of lung adenocarcinoma cells." (PMID 41413918, 2025). "Furthermore, we showed that FDI-6 alters cell proliferation and inhibits the activities of FOXM1 as well as MYBL2 in lung adenocarcinoma cells." (PMID 36291764, 2022). "Moreover, we identified novel downstream targets of MYBL2 and FOXM1 that include key oncogenes such as CENPA in lung adenocarcinoma." (PMID 36291764, 2022). "However, our results, which show that FDI-6 treatment changes the expression of key genes and proteins involved in the cell cycle, suggest that MYBL2 and FOXM1 are potential treatment targets for lung adenocarcinoma." (PMID 36291764, 2022). "In addition to CENPA, we identified additional potential target genes of MYBL2 and FOXM1 in lung adenocarcinoma." (PMID 36291764, 2022). "Taken together these data indicate the FoxM1 and its transcriptional activity may represent a therapeutic target for KRASm/WT+ lung adenocarcinomas." (PMID 34573384, 2021). "Moreover, m6A demethylase ALKBH5 expression was elevated in lung adenocarcinoma, and the m6A level was upregulated in forkhead box M1 (FOXM1) mRNA." (PMID 34001850, 2021). "In conclusion, berberine could significantly inhibit the survival of lung adenocarcinoma through FOXM1." (PMID 35173608, 2021). "Moreover, ALKBH5 downregulates the m6A enrichment on FOXM1 mRNA and promotes cell proliferation and invasion in lung adenocarcinoma." (PMID 33428593, 2021). "Furthermore, the inferred activity of FOXA2, FOXM1, and UHRF1 were significantly associated with survival in several lung adenocarcinoma cohorts." (PMID 31503425, 2019). "Owing to the great importance of the FOXM1/MET/AKT axis in lung adenocarcinoma, our findings strongly indicate that targeting FOXM1 may be a promising therapeutic strategy for overcoming gefitinib resistance in lung adenocarcinoma." (PMID 27494877, 2016). "Considering our experimental results and previous publications, it can be concluded that the inhibitory role of DACH1 in the proliferation and invasion of lung adenocarcinoma should be ascribed to the downregulation of its transcriptional target, Prx3, by competing with FOXM1 for promoter binding." (PMID 26810067, 2016). "Additionally, MET activated and triggered the AKT signaling pathway, which subsequently stimulated FOXM1 expression in lung adenocarcinoma cells, and this effect was partially inhibited by LY294002." (PMID 27494877, 2016). "PPARα mRNA was also increased in Foxm1-depleted A549 lung adenocarcinoma cells in vitro." (PMID 19672312, 2009). "Furthermore, inhibition of FOXM1 increases the sensitivity of lung adenocarcinoma to gefitinib." (PMID 39594778, 2024). "Furthermore, we tested whether FDI-6 affects FOXM1 activity in A549 lung adenocarcinoma cells by performing Western blot experiments using FDI-6-treated nuclear extracts." (PMID 36291764, 2022). "Moreover, MET/AKT pathway upregulated the expression of FOXM1 in lung adenocarcinoma cells." (PMID 27494877, 2016). "Therefore, we hypothesized that FOXM1 might be involved in gefitinib resistance of lung adenocarcinoma cells." (PMID 27494877, 2016). "In addition, new researches have verified that Foxm1 directly bound to and increased activity of Snail1 promoter, namely Snail1 is a direct downstream transcriptional target of Foxm1 in the radiation-induced pulmonary fibrosis and lung adenocarcinoma progression." (PMID 25935853, 2015). "The results revealed that MYBL2, CENPA, FOXM1, E2F1, ZNF367, and HMGA1 are the most relevant upstream transcription factors in lung adenocarcinoma." (PMID 40885709, 2025).
lung adenocarcinoma (continued). "CTCF, MLLT1, and TGIF2 are transcriptional regulators that play crucial roles in the transcription of important proto-oncogenes such as FOXM1, MYC, HoxA gene family, and OCT4 in multiple cancer types including HCC, esophageal cancer, and lung adenocarcinoma." (PMID 37335919, 2023). "This additive effect upon knockdown of both FOXM1 and MYBL2 suggests that these factors work together as transcriptional activators in lung adenocarcinoma cells." (PMID 36291764, 2022). "Compared to normal tissues, either in lung adenocarcinoma (LUAD) or lung squamous cell carcinoma (LUSC), the expression of FOXM1 is at a higher level." (PMID 36292640, 2022). "Further studies to characterize the mechanisms of MYBL2 and FOXM1 target genes and to determine the effectiveness of FDI-6 in lung adenocarcinoma patients are needed." (PMID 36291764, 2022). "Most of the genes were significantly reduced by the knockdown of both MYBL2 and FOXM1 in A549 and NCI-H2126 lung adenocarcinoma cells." (PMID 36291764, 2022). "We further used lung adenocarcinoma (LUAD) tissues combined with quantitative real-time PCR (qRT-PCR) and immunohistochemistry (IHC) for experimental validation of FOXM1 expression." (PMID 36435510, 2022). "Lastly, we assessed potential treatment options for the disease by treating lung adenocarcinoma cells with an inhibitor targeting MYBL2 and FOXM1." (PMID 36291764, 2022). "In conclusion, it is suggested that FDI-6 can change the expression of genes involved in cell cycle regulation, affecting the activity of both FOXM1 and MYBL2 in lung adenocarcinoma cells." (PMID 36291764, 2022). "We furthermore investigated the effect of a previously reported FOXM1 inhibitor, FDI-6, in lung adenocarcinoma cells." (PMID 36291764, 2022). "In accordance with the previous finding that MYBL2 and FOXM1 control genes expressed in the G2/M phase of the cell cycle, we found that MYBL2 and FOXM1 regulate genes belonging to the G2/M phase in lung adenocarcinoma cells." (PMID 36291764, 2022). "It is also the first time to confirm the significance and relationship of FOXM1 and its target gene POLE2 in lung adenocarcinoma." (PMID 35173608, 2021). "M6A demethylase ALKBH5 affected the proliferation and invasion of lung adenocarcinoma cells by downregulating m6A modification on FOXM1 (HGNC:3818) mRNA and promoting FOXM1 expression." (PMID 35087827, 2021). "On the other hand, FOXM1 and UHRF1 were activated in lung adenocarcinoma, with increased expression of their positive targets and/or decreased expression of their negative targets." (PMID 31503425, 2019). "Our findings also suggest the existence of a novel positive feedback loop, which consists of FOXM1 and MET/AKT signaling in lung adenocarcinoma cells." (PMID 27494877, 2016). "In the study, we investigate the role of FOXM1 in the resistance of lung adenocarcinoma cells to gefitinib, and define a novel regulatory pathway directly linking the MET/AKT signaling axis to FOXM1." (PMID 27494877, 2016). "Further statistical analysis indicated that the level of FOXM1 is significantly correlated with that of MET and with the activity of the AKT pathway in human lung adenocarcinoma specimens." (PMID 27494877, 2016). "Fourth, FOXM1 was a downstream target of AKT signalling, and there was a positive feedback regulation between FOXM1 and the MET/AKT signaling pathway in lung adenocarcinoma cells." (PMID 27494877, 2016). "Taken together, FOXM1 lies both downstream and upstream of MET/AKT signaling pathway, and creates a positive feedback loop to promote gefitinib resistance in lung adenocarcinoma cells." (PMID 27494877, 2016). "In this study, the GPSAdb database was employed to identify the upstream gene FOXM1, which may induce changes in MRPL13 expression after knockout in lung adenocarcinoma cell lines." (PMID 37827692, 2023). "Next, we assessed potential treatment options for lung adenocarcinoma targeting MYBL2 and FOXM1." (PMID 36291764, 2022).
lung adenocarcinoma (continued). "We further examined the expression levels of the identified MYBL2 and FOXM1 target genes in lung adenocarcinoma tissues and adjacent normal lung tissues using TCGA RNA-seq datasets." (PMID 36291764, 2022). "Furthermore, we showed that the binding sites of another transcriptional activator, FOXM1, are largely shared with MYBL2 binding sites in lung adenocarcinoma cells." (PMID 36291764, 2022). "Moreover, we found that a previously reported FOXM1 inhibitor, FDI-6 (forkhead domain inhibitor 6), suppresses lung adenocarcinoma cell proliferation by inhibiting the activities of MYBL2 and FOXM1 and controlling cell death and cell cycle genes." (PMID 36291764, 2022). "In addition, we demonstrated that the therapeutic target of berberine was to inhibit the expression of FOXM1 and POLE2 mediated by FOXM1, so as to intervene the survival of lung adenocarcinoma (Overview of this study)." (PMID 35173608, 2021). "However, in lung adenocarcinoma, ALKBH5 directly downregulates the m6A modification of FOXM1 mRNA and promotes FOXM1 expression under intermittent hypoxia." (PMID 33428593, 2021). "ALKBH5 was also elevated in lung adenocarcinoma cells under intermittent hypoxia, and the knockdown of ALKBH5 inhibited the proliferation and invasion of lung adenocarcinoma cells via reducing the m6A level of FOXM1." (PMID 32742194, 2020). "Furthermore, the study showed that depleting FOXM1 expression decrease the TOP2A mRNA and protein level in A549 human lung adenocarcinoma cells." (PMID 31681566, 2019). "We analyzed the significance of the FOXM1/MET/AKT axis in a total of 64 pairs of lung adenocarcinoma specimens and adjacent non-cancerous specimens." (PMID 27494877, 2016). "Finally, we found that FOXM1, MET and pAKT were concomitantly overexpressed in lung adenocarcinoma specimens." (PMID 27494877, 2016). "To determine whether our findings have clinical relevance in human lung adenocarcinoma, we investigated the expression of FOXM1, MET and pAKT in human lung adenocarcinoma samples." (PMID 27494877, 2016). "We further investigated whether FOXM1, an oncogenic transcription factor, regulated MET expression via transcription in lung adenocarcinoma cells." (PMID 27494877, 2016). "Taken together, our results indicate that FOXM1 promotes acquired resistance to gefitinib of lung adenocarcinoma cells, and FOXM1 crosstalks with MET/AKT signaling to form a positive feedback loop to promote lung adenocarcinoma development." (PMID 27494877, 2016). "In addition, it was found that CENPE was highly expressed in lung adenocarcinoma tissues, the proliferation of lung adenocarcinoma cells was inhibited by suppression of CENPE expression, and the expression of FOXM1 was also directly correlated with the expression of CENPE." (PMID 37335738, 2023). "Also, in the same set of lung adenocarcinoma specimens and adjacent non-cancerous specimens, we examined the expressions of FOXM1, MET and pAKT by western blot and immunohistochemical analyses." (PMID 27494877, 2016). "We also found that FOXM1 was regulated by MET through PI3K/AKT signaling pathway and that the feedback regulation loop between FOXM1 and MET/AKT signaling pathway could play a pivotal role in gefitinib resistance of lung adenocarcinoma cells." (PMID 27494877, 2016). "Thus, our findings elucidated a novel FOXM1/MET/AKT regulatory feedback loop and identified that FOXM1 might be a target for overcoming gefitinib resistance in lung adenocarcinoma." (PMID 27494877, 2016). "Moreover, we demonstrated that expression levels of FOXM1, MET and pAKT were significantly higher in lung adenocarcinoma tissues than in normal lung tissues, and these three biomarkers were concomitantly overexpressed in lung adenocarcinoma tissues." (PMID 27494877, 2016).